CD4 (CD4 molecule)
Diseases named in the same sentence as CD4 in open-access papers (continued):
Sharing a sentence is not in itself a finding about the gene and the disease.
tumor (continued). "MDSCs facilitate tumor growth and metastasis by secreting cytokines that exert immunosuppressive effects on CD4+ and CD8+ T cells." (PMID 39545407, 2024). "We treated a two-tumor mouse model with anti-Her2 CAR T cells (CD8+) along with a suppressor T cell (CD4+) expressing an anti-CD19 synNotch→TGFβ1+CD25 circuit." (PMID 39636990, 2024). "Findings indicated that the Low ac4C cluster exhibited significantly higher levels of tumor-infiltrating immune cell, including CD4, CD8, and macrophages, along with elevated immune function activation." (PMID 39648231, 2024). "The results showed that in tumor samples and tumor-infiltrating CD4 T cells, these genes were significantly over-expressed in hypermetabolic regions." (PMID 38287007, 2024). "In contrast, control mice had a cumulative decline in tumor-infiltrating CD4+ Tconv cells and a concurrent increase in Tregs on D23 compared to D14." (PMID 38518770, 2024). "ICT- and neoAg SLP vax-induced tumor rejection was dependent on both CD4 and CD8 T cells, since depleting either subset abolished therapeutic efficacy." (PMID 39446585, 2024). "C002 treatment also increased the tumor infiltration of CD44(+)CD4(+) T cells, suggesting a shift from naïve to effector/effector memory T cell populations." (PMID 38895115, 2024). "Ruminococcaceae improves the infiltration of CD8+ T cells within tumors, induces the differentiation of effector CD4+ and CD8+ T cells, and enhances the ratio of CD8+/FOXP3+CD4+ in tumor-infiltrating T cells." (PMID 38617841, 2024). "In the lepidic pattern, the NECTIN2-TIGIT interactions involved tumor cells and NK and Tregs cells, and the interactions extended to encompass tumor cells and CD4+ T/CD8+ T cells with the histologic pattern progression." (PMID 39474422, 2024). "Compared with Group D, we found an enormous elevation in both CD8+ T cell and CD4+ T cell fractions of distal tumor and spleen in Group E, suggesting that RENPs relieved immune tolerance and promoted an effective antitumor immune response." (PMID 38774946, 2024). "In the tumor microenvironment of pancreatic cancer, the infiltrating lymphocytes are mainly T lymphocytes, including CD4+ helper T lymphocytes (Th), regulatory T cells (Treg) and CD8+T lymphocytes." (PMID 39744013, 2024). "Lower doses are furthermore superior in enabling CD4+ and CD8+ T-cell tumor infiltration and changing tumor-associated macrophages from an immune inhibitory M2-like polarization toward an immune stimulatory M1-like phenotype." (PMID 39086395, 2024). "In the effector phase of the immune response triggered by tumor-primed CD4+ T cells that were transferred adoptively, both tumor Tregs and naive Tregs are unable to suppress antitumor immunity." (PMID 39664195, 2024). "In this study, we demonstrated that the infection of B16F10 tumor cells with the rLaSota-BC-RFP virus increased the infiltration of CD8+ and CD4+ T cells in the tumor tissues, accompanied by elevated levels of IL-12, IFN-γ, IL-15, TNF-α, and IL-18." (PMID 39458338, 2024). "Higher levels of PD-L1 were observed in both tissues harboring mutant KRAS and tumor tissue-derived CD4+ and CD8+ T-cells in mouse models." (PMID 39272910, 2024). "Optimizing vaccine design (antigen and adjuvant selection), concentrating on the role of CD4+ T cells in tumour vaccines, and combination immunotherapy will become new keys to increasing the efficacy of GBM vaccines." (PMID 38183840, 2024). "Th1 and Th2 helper T cells are two different subpopulations of CD4 + cells among tumor-infiltrating lymphocytes." (PMID 38822944, 2024). "Analysis of CD4+ T cells showed enhanced infiltration in the VNP@Sgc8c-MMAE treated group, with a marked decrease in CD4+ Tregs, suggesting a reduction in immunosuppressive cell populations within the tumor microenvironment." (PMID 39397032, 2024).
tumor (continued). "This SiRNA-AuNPs combination showed promising immunotherapeutic potential, as indicated by the increased infiltration of CD8+ and CD4+ T cells in both spleen and cancerous tissue, suggesting T-cell activation against tumor cells." (PMID 40808797, 2024). "The anti-tumor efficiency of tumor-infiltrating CD4+T cells was determined by an LDH release assay and flow cytometry on passage-matched tumor cells." (PMID 38891044, 2024). "CD4 helper T cells exhibit a tumor-promoting Th2 phenotype and are abundant in the TME in comparison to CD8 T cells." (PMID 38434964, 2024). "NLRP3 leads to the differentiation of tumor-promoting CD4+ T cell subsets (Th2, Th17, and regulatory T cells)." (PMID 37524704, 2023). "Several preclinical studies showed that mild hyperthermia results in reduced tumor growth and improved animal survival, in parallel with enhanced infiltration and activation of immune cell populations including natural killer (NK), CD4+ T, and CD8+ T cells." (PMID 37686590, 2023). "TILs composed of NK cells, CD8+ cytotoxic T cells, and CD4+ helper T cells, are essential players in the defense against tumor cells." (PMID 36982677, 2023). "And the expression of IGF2BP3 was significantly correlated with tumor purity (cor=0.094, P=4.03e-02) and CD4+ T cells (cor=0.19, P=2.07e-05)." (PMID 36793593, 2023). "Corresponding to RNA expression results, CD4+ T cell co-culture induced PD-L1 in tumor cells, and the induction was further upregulated in presence of Cd4;Tcf7fl/fl T cells." (PMID 36239683, 2023). "The results showed that the expression of m7GRGs was closely related to tumor-infiltrating immune cells, which included CD4+ T cells, CD8+ T cells, B cells, NK cells, macrophages, myeloid dendritic cells, monocytes, endothelial cells, and neutrophils." (PMID 36816047, 2023). "In the tumor samples, CD4+ T cells were already more prevalent than CD8+ T cells (34% vs. 19.5%), and in pre-REP TILs and REP TILs, the CD4+ T cell dominance further increased (46.8% and 68.4%, respectively)." (PMID 37484198, 2023). "The expression pattern of MHC molecules in tumour tissues should therefore also determine the spatial distribution and migratory behaviour of adoptively transferred CD4+ and CD8+ T cells." (PMID 37316667, 2023). "A likely interaction partner for CD4+ T cells are dendritic cells due to their ability to efficiently ingest and process tumour antigens for MHC-II-dependent antigen presentation." (PMID 37316667, 2023). "Immune cells such as tumor-infiltrating T cells (CD4+/CD8+ T cells), M1 macrophages, and NK cells have been shown to be associated with immune responses." (PMID 36909170, 2023). "Although the dominant role of cytotoxic CD8 T cell response has been suggested in the efficacy of tumor cell elimination, immune responses engaging CD4 T cell response have been gaining more relevance with growing knowledge in tumor immunology." (PMID 37035178, 2023). "Prior work found that anti-PD-L1 therapy enhances the activity of CD4+ T cells, leading to increased tumor infiltration and improved anti-tumor activity." (PMID 37689790, 2023). "Foxp3+CD4+CD25+CD127low/- T cells showed significantly positive correlation with AFP, associated with tumor size in HBV-HCC patients." (PMID 38090482, 2023). "We have also analyzed effector and central memory populations of CD4+ and CD8+ T lymphocytes and a significant decrease in effector tumor-associated Tc lymphocytes was observed after nsCaEP treatment when compared to CTRL mice." (PMID 37630998, 2023). "Tumours harbouring PD-L1+ TILs were also the ones displaying higher CD4+/FOXP3+ (49.0 vs. 8.2 cells/mm2, p = 0.002) and CD8+/PD-1+ TIL cell density (40.8 vs. 12.3 cells/mm2, p = 0.016)." (PMID 37274775, 2023). "As reported, IL2-stimulated CD4+ T cell-derived EVs played certain roles in anti-tumor immune responses via increasing the cytotoxicity of CD8+T cell." (PMID 37575250, 2023).
tumor (continued). "The mesenchymal score was negatively correlated with anti-tumor activated CD4 and activated CD8 T cells, indicating that the T cell activation process is altered in tumors with high mesenchymal scores." (PMID 37884639, 2023). "Here the authors show that cDC1 encounter with CD4+ helper T-cells transforms their gene expression signature, and these “helped” dendritic cells enable the function of anti-tumour cytotoxic T-cells." (PMID 36639382, 2023). "Appropriately given the name DC vaccines, these vaccines can elicit an anti-tumor response by activating CD4+ and CD8+ T cells." (PMID 37046685, 2023). "Regardless, the finding that CD4+ CTLs are predisposed to invoke B cells and mediate humoral immunity through CXCL13 expression emphasizes their central role in tumor immunity in addition to their CD8+ CTL counterparts." (PMID 38077321, 2023). "Specifically, we observed direct changes in the tumor microenvironment after using a ferroptosis inducer in this tumor subtype with the recruitment of CD3e+, CD4+, CD8+, and CD86+ cells, and a reduced number of CD206+ cells." (PMID 36861444, 2023). "Th2 subtype CD4+ T-cells and Treg cells also have anti-tumor immune responses that suppress CTL and NK cells." (PMID 36966334, 2023). "CD4+ T cells that promote their activation and proliferation and their synergistic antitumor activity are considered to be essential for tumor surveillance." (PMID 37342362, 2023). "We suggest that exclusion of CD4+FOXP3+ cells is a tumour-permissive requirement mandatory for the maintenance of tumour-driving chronic antigenic stimulation and LP : Tfh cell interactions." (PMID 37854674, 2023). "In NSCLC patients and mouse syngeneic tumor models, large numbers of meflin+ CAFs attracted greater CD4+ T cell infiltration and promoted tumor angiogenesis, which in turn enhanced the response of NSCLC to immune checkpoint blockade therapy." (PMID 37143134, 2023). "Flow cytometry of Ki tumor-bearing lungs revealed that lung tumor-associated CD4+, CD8+, and Treg cells expressed increased PD-1, as did CD4+, CD8+, Treg, and myeloid cells in the tumor-draining mediastinal lymph node." (PMID 36746936, 2023). "CD4+ T cells recruit tumor-specific CD8+ T cells and activate CD8+ effector T cells and NK cells to kill tumor cells." (PMID 36892747, 2023). "A subset of CD4+ T cells develops cytolytic effector functions towards MHC-II-expressing tumour cells." (PMID 37316667, 2023). "The effect in vivo included the increased infiltration of CD8 + and CD4 + T cells, tumor progression arrest, the inhibition of lung metastasis, and a remarkable increased overall survival." (PMID 36854896, 2023). "It has been reported that the increased abundance of both CD4+ and CD8+ T cells in tumor are associated with improved responsiveness to BCG." (PMID 37566017, 2023). "Several studies highlight a positive correlation between increased infiltration and high densities of CD3+ T cells (effector CD4+ or CD8+ T cells) at tumor sites to disease-free survival in CRC patients." (PMID 38074634, 2023). "Blockade of FATP2 inhibited NLRP3 activation in MDSCs, IL-17 production in CD4+ T cells, and the tumour recurrence post fatty liver IRI." (PMID 37916155, 2023). "The presence of CD8+ T cells is known to induce apoptosis of cancer cells, and CD4+ T cells are known for their helping function in maintaining the anti-tumor role of CD8." (PMID 36769287, 2023). "A pliot study conducted by us also has shown that MTT induces functional maturation of DCs, promotes CD4+ T-cell-mediated anti-tumor responses, and reduces regulatory T cells (Tregs), thereby improving treatment outcomes in colorectal cancer patients." (PMID 37334386, 2023). "LncRNAs modulating CD4+ T cell subsets in a tumor context-dependent manner is a newly emerging field of research." (PMID 37346034, 2023).
tumor (continued). "Adaptive anti-tumor immunity is principally based on mature dendritic cells (DCs), macrophages, tumor-specific CD4+ T helper 1 cells (Th1), CD8+ cytotoxic T cells (CTLs), and cytotoxic antibody (Ab)-producing B cells." (PMID 36677048, 2023). "We proposed that most tumor-infiltrating Tregs were differentiated from in situ and peripheral CD4+ naïve T cells and activated via CD70-CD27 signaling." (PMID 37024479, 2023). "Taken together, we discovered a subset of CD4+ T cells that can modulate anti-tumor immunity and predict immunotherapy responses by the integrative analysis of the resources in TIGER." (PMID 36049666, 2023). "Tumor centers had significantly higher proportions of memory activated CD4+ T cells, follicular helper T cells, and M0 and M1 macrophages, compared to both the negative margins and the adjacent normal tissues." (PMID 37392167, 2023). "As for lung adenocarcinoma, the differentiation of tumor-specific CD4+ T follicular helper cells under the stimulation of B cells in a neoantigen-dependent manner, which promote CD8+ T cell effector functions and drive anti-tumor immunity." (PMID 38082437, 2023). "We used immunohistochemistry to detect the different expressions of CD3 and CD4 in the tumor tissues of the two groups." (PMID 37345110, 2023). "Mechanistically, ARID1A mutation correlated with extensive DNA damage repair deficiency and immunogenic tumor microenvironment (TME) featured by elevated activated subsets of CD8+ T cells, CD4+ T cells, and NK cells." (PMID 36369379, 2023). "The major cellular players mediating GBM immunosuppression are CD4+ CD25+ Foxp3+ T regulatory cells (Tregs), myeloid-derived suppressor cells (MDSCs), and M2 polarized tumor-associated macrophages (TAMs)." (PMID 37114043, 2023). "in different tumor models demonstrated that cytotoxic features of tumor-reactive CD4+ Th1 cells can develop also independently of Eomes." (PMID 37965314, 2023). "This is of particular interest in the context of TLR4 research, as PD-L1 has also been shown to block the cytolytic activity of PD-1+ tumor infiltrating CD4+ and CD8+ T cells, which are reliant on dendritic cell -TLR4 interaction." (PMID 35841426, 2023). "In previous work, our group has demonstrated that B cells from SN in patients with cancer are activated and show clonal expansion specifically against the tumor, as well as that B cells in SN activate CD4+ T-cell-mediated anti-tumor responses." (PMID 36765877, 2023). "Next, we found that typical pro-tumor cells, such as M2 macrophages, memory CD4 T cells resting, and mast cell resting were significantly highly infiltrated in C2." (PMID 37274274, 2023). "Conversely, one study has demonstrated that CD4+ T-cell infiltration at the tumor edge is significantly higher than in the tumor center in both ICCA and extrahepatic CCA (eCCA)." (PMID 38213535, 2023). "This article reviews the relevant research on the heterogeneity of CD4+Treg, subtype classification, and their relationship with tumor therapy." (PMID 38250084, 2023). "GK-1 increased the levels of IL-2 and IFN-γ produced by tumor-related CD4+ and the levels of GZB and IFN-γ produced by tumor-related CD8+ T lymphocytes." (PMID 37736849, 2023). "We then isolated CD4+ T cells from the spleen, lymph nodes, and blood of healthy mice and tumor-bearing mice and investigated the expression of Tcf7, Lef1, and Axin2." (PMID 36239683, 2023). "IDO1 as the key enzyme in tryptophan metabolism plays a vital role in differentiating CD4+ T cells into regulatory T cells in tumors, thereby promoting the immunosuppressive state of the tumor microenvironment." (PMID 37040510, 2023). "Following the course of treatment, assessment of the immunomodulatory effect typically focuses on the CD8+ and CD4+ T cells in the tumor, spleen, and lymph nodes." (PMID 37251920, 2023).
tumor (continued). "Consistently, the rate of tumor-infiltrating immunosuppressive regulatory T cells (Tregs, CD4+Foxp3+) in MTHMS + L group declined obviously in comparison with the other groups." (PMID 37221157, 2023). "Several studies have shown CXCL13+ T cells are tumour reactive and co-expression of CD39 and CXCL13 allows effective enrichment of tumour reactive CD4+ T cells in NSCLC." (PMID 37520560, 2023). "According to CIBERSORT, tumor sample with high immune score were enriched with CD4+ and CD8+ T cells." (PMID 36058633, 2023). "Intralesional injection of T-VEC has been shown previously to impact the tumor microenvironment by inducing an oncolytic immune-mediated effect, as shown by increased circulating CD4+ and CD8+ T cells." (PMID 37292376, 2023). "Further multiplexed immunofluorescence staining of the CD3/CD4/CD8A/CD68/CCL4 markers validates the immune-activated state in the tumor thrombus samples." (PMID 37244923, 2023). "For instance, CD4+ T cells have been demonstrated to directly lyse tumour cells, possess enhanced in vivo persistence relative to CD8+ T cells and in some models, elicit superior anti-tumour activity compared with CD8+ T cells." (PMID 37684239, 2023). "Pancancer single‐cell RNA sequencing (scRNA‐seq) data were used to identify the clusters of CD4+ T cells in the tumour microenvironment (TME)." (PMID 37313656, 2023). "We found tumor-infiltrating T-cells (CD4, CD8), TAMs, MDSCs, and immune checkpoints including PD1, Lag3, and CTLA4 in C0321 tumors." (PMID 37901240, 2023). "Tregs are a subtype of CD4+ helper T cells that control autoimmunity by suppressing conventional T cells, creating an immunosuppressive environment that promotes tumor progression." (PMID 37173918, 2023). "In both datasets, the infiltration of activated CD4 memory cells, regulatory T cells, and M0/M1 macrophages in the tumor samples increased significantly, while the infiltration of monocytes and resting mast cells was significantly reduced." (PMID 36708047, 2023). "Both preclinical and clinical investigations have established the direct anti-tumor effects of CD4+ on CTLs by the release of cytotoxic granules containing granzyme B and perforin." (PMID 38213535, 2023). "This pilot study is the first to identify RT-induced changes in the phenotypic profiles of circulating CD8+ and CD4+ T cells in NPC patients and their association with post-RT plasma EBV DNA clearance and tumor recurrence." (PMID 36980772, 2023). "The numbers of tumor nodules and liver weights were also significantly increased in Chatfl/fl; Cd4-cre mice." (PMID 37640929, 2023). "Unexpectedly, we observed increased proportions of monocytes and IFNγ+CD44+ CD4+ T cells in anti–PD-1-treated KB1P tumor-bearing mice." (PMID 36480166, 2023). "This suggests that CD4+ T are primarily responsible for the αTim-3-enhanced anti-tumor response of S100." (PMID 37771774, 2023). "Consistent with the notion that CD4+ T cells are critical for NEC immunization-mediated tumor control, CD4+ T cell infiltration was reduced in Ifnar1−/− mice compared to WT controls." (PMID 38196632, 2023). "Improved tumor infiltration by CD4+ and CD8+ T cells was observed after a combined treatment with low doses of paclitaxel and DC vaccination in a lung carcinoma xenograft model." (PMID 37173937, 2023). "Remarkably, animal experiments showed similar trends, as reduction in tumor weight and volume, as well as tumor cell numbers, inhibition of CD4+ and CD8+ T cells, and macrophage M2‐type polarization upon silencing YAP." (PMID 37329188, 2023). "Adoptive transfer of tumor-antigen-specific CD4 T cells has been reported to potently control tumor progression." (PMID 37185301, 2023). "Taken together, our study provides compelling evidence for CD8-independent tumor control by human CD4 T cells in vivo and offers a valuable preclinical tool to explore therapeutic strategies to enhance CD4 CTL differentiation and function." (PMID 37185301, 2023).